SLC5A8 (solute carrier family 5 member 8)
Diseases named in the same sentence as SLC5A8 in open-access papers (continued):
Sharing a sentence is not in itself a finding about the gene and the disease.
cancer (27 papers, 2005 to 2026). A tumor composed of atypical neoplastic, often pleomorphic cells that invade other tissues. "The expression of SLC5A8 in cancer cells is silenced by hypermethylation, and the gene silencing of SLC5A8 by hypermethylation is associated with poor prognosis." (PMID 39061990, 2024). "Suppression of the SLC5A8 gene is linked to DNA methylation, and treatment of cancer cells with DNA demethylating agents increases SLC5A8 expression." (PMID 35625705, 2022). "Silencing the SLC5A8 is associated with DNA methylation, and treatment of cancer cells with DNA demethylating agents increases the SLC5A8 expression." (PMID 35625705, 2022). "SLC5A8 is a sodium-coupled mono carboxylate transporter; methylation of the SLC5A8 gene is essential in human cancers, and the protein encoded by this gene shows structural features of a sodium-iodide symporter with 48% homology to SLC5A5 (610 amino acids)." (PMID 28926589, 2017). "Based on bioinformatics analysis and gene characterization, and specifically because of its association with cancer, we targeted the gene SLC5A8 for further study." (PMID 27777899, 2016). "This may be due to the fact that the expression of SLC5A8 (the gene coding for the Na + −coupled pyruvate transporter that regulates the entry of blood-borne pyruvate into cancer cells) is variant in CCA cells." (PMID 30866966, 2019). "Hypermethylation silences the expression of SLC5A8 in cancer cells, and gene silencing of SLC5A8 by hypermethylation was associated with poor prognosis." (PMID 39061990, 2024). "Another member of the solute carrier family, SLC5A8, was downregulated in cancer samples (log2FC = −6.09 × 10−1; adjusted p-value = 1.24 × 10−21)." (PMID 39408960, 2024). "The methylation status of SLC5A8 has been reported in various cancers, including thyroid, esophageal, and breast cancer." (PMID 38007446, 2023). "Different SLC5A8 expression in cancer cell lines would declare why apoptosis is apparent inconsistently." (PMID 28591165, 2017). "SLC5A8, a cancer suppressor gene with decreased expression among infected children, was chosen for further study based on bioinformatics analysis." (PMID 27777899, 2016). "In our investigation, mutation carriers over 50 years old with a previous CRC diagnosis showed a significantly elevated average degree of methylation of SFRP1 and SLC5A8 vs. cancer-free individuals of a comparable age." (PMID 26203307, 2015). "They include also transporters as SLC5A8 and, conceivably, other monocarboxylate-specific transporters whose expression is modulated in cancer cells." (PMID 23762063, 2013). "The plasma membrane transporter SLC5A8 was reported to be downregulated in different human cancer cells." (PMID 23762063, 2013). "Lowered levels of SLC5A8 potentially lead to the promotion of carcinogenesis and hypothetically may affect the efficiency of radioactive iodine treatment of cancer patients." (PMID 40869209, 2025). "SLC5A8 was also shown to transport putative anti-cancer drugs 3-bromopyruvate and dichloroacetate." (PMID 40869209, 2025). "Another important cancer marker in determining the effectiveness of VPA could be the SLC5A8 co-transporter, which acts as an electrogenic sodium- and chloride-dependent sodium-coupled co-transporter." (PMID 35625705, 2022). "Our demonstration that 2,4,6-THBA inhibits cell growth in cancer cells expressing functional SLC5A8 suggests that such a phenomenon may indeed exist in vivo and may contribute to its anti-cancer effects against CRC." (PMID 30917530, 2019). "The high affinity lactate transporter SMCT1 (SLC5A8, GeneID: 160728) favors the import of lactate and is suppressed in a number of cancer cell types, as summarized in." (PMID 24653705, 2014). "Our results, for the first time demonstrate a role for flavonoid metabolites in the inhibition of cancer cell growth occurring through both CDK-dependent and -independent mechanisms, and also establishes a functional role for SLC5A8 in the transport of 2,4,6-THBA." (PMID 30917530, 2019).
cancer (continued). "Of these only 3,4-DHBA and 3,4,5-THBA inhibited cancer cell proliferation and this was independent of both SLC5A8 transport and CDK inhibition." (PMID 30917530, 2019). "SLC5A8 was not included in Recon 2, most likely because this protein has been mainly discussed in the context of cancer." (PMID 24653705, 2014). "SLC5A8 and SLC5A12 transporters mediate uptake of a variety of monocarboxylates including benzoic acid and show different concentration profiles in normal vs. cancer tissues." (PMID 24954394, 2014). "To investigate further the role of promoter DNA methylation of genes aberrantly hypermethylated in cancer in hESCs, we compared the DNA methylation and expression status of four of the genes identified in the methylation arrays (MGMT and SLC5A8 from Class B-I, and PYCARD and RUNX3 from Class B-II)." (PMID 18820729, 2008). "Interestingly, the other two metabolites, 3,4-DHBA and 3,4,5-THBA, which failed to inhibit CDK activity, potently inhibited cancer cell proliferation independent of a functional SLC5A8." (PMID 30917530, 2019).
adenocarcinoma (1 paper, 2011). A common cancer characterized by the presence of malignant glandular cells. "Tubulovillous, tubular, adenocarcinoma and polyps all showed a similar level of SLC5A8 methylation (∼80%) that was comparable to the value with the entire 50 samples analyzed here." (PMID 21687703, 2011).
infection (1 paper, 2016). The state of being infected such as from the introduction of a foreign agent such as serum, vaccine, antigenic substance or organism. "Potentially, therefore, one may speculate that loss of SLC5A8 expression induced by H. pylori should promote cell proliferation and inflammation, which in turn could favor the infection process and enhance severity of the infection." (PMID 27777899, 2016).
metabolic disorders (1 paper, 2019). "Erysipelotrichaceae have been associated with inflammatory diseases and metabolic disorders, both in humans and mice; this bacterial strain is also present in greater abundance in Slc5a8-null mice when fed the fiber-free diet." (PMID 31976310, 2019).
SLC5A8 also shares sentences with these, for which no sentence is quoted: bladder cancer (2 papers); colorectal tumor (2); Hypertension (2); Insulin resistance (2); Obesity (2); acute myeloid leukemia (1); benign thyroid tumors (1); brain tumors (1); cholangiocarcinoma (1); diabetes mellitus (1); diabetic nephropathy (1); diarrheal disease (1); follicular thyroid cancer (1); gastrointestinal disorders (1); Hyperglycemia (1); Hyperinsulinemia (1); hyperuricemia (1); Immunodeficiency (1); kidney diseases (1); morbid obesity (1); non-small cell lung carcinoma (1); prostate tumors (1); schistosomiasis (1); Sleep apnea (1); Thyroid adenoma (1); type 2 diabetes (1).